CPSF7 (cleavage and polyadenylation specific factor 7)
Description:
Component of the cleavage factor Im (CFIm) complex that functions as an activator of the pre-mRNA 3'-end cleavage and polyadenylation processing required for the maturation of pre-mRNA into functional mRNAs. CFIm contributes to the recruitment of multiprotein complexes on specific sequences on the pre-mRNA 3'-end, so called cleavage and polyadenylation signals (pA signals). Most pre-mRNAs contain multiple pA signals, resulting in alternative cleavage and polyadenylation (APA) producing mRNAs with variable 3'-end formation. The CFIm complex acts as a key regulator of cleavage and polyadenylation site choice during APA through its binding to 5'-UGUA-3' elements localized in the 3'-untranslated region (UTR) for a huge number of pre-mRNAs. CPSF7 activates directly the mRNA 3'-processing machinery. Binds to pA signals in RNA substrates.
Synonyms: CFIm59; FLJ12529
Tractability: PROTAC: UniProt records ubiquitination sites on it; ubiquitination databases record sites on it; its protein half-life has been measured.
Gene: Protein-coding gene on chromosome 11 (61,402,641 to 61,430,105, reverse strand). Ensembl gene ENSG00000149532.
Subcellular location: Nucleus; Cytoplasm
Subcellular location (Human Protein Atlas): Nucleoplasm; Cytosol
Pathways (Reactome):
Metabolism of RNA: Processing of Intronless Pre-mRNAs; mRNA 3'-end processing; mRNA Polyadenylation
Disease: Dengue Virus-Host Interactions
Gene expression (Transcription): RNA Polymerase II Transcription Termination
Signal Transduction: RHOBTB1 GTPase cycle
Gene Ontology:
Molecular function: protein binding; RNA binding; mRNA binding; nucleic acid binding
Biological process: co-transcriptional mRNA 3'-end processing, cleavage and polyadenylation pathway; mRNA 3'-end processing; mRNA alternative polyadenylation; protein heterotetramerization; protein tetramerization
Cellular component: cytoplasm; cytosol; membrane; mRNA cleavage and polyadenylation specificity factor complex; mRNA cleavage factor complex; nucleoplasm; nucleus
Genetic constraint (gnomAD): Loss-of-function variants: 1 observed, 36.35 expected, observed/expected ratio (o/e) 0.0275, 90% interval 0.009 to 0.13. The upper end of that interval is the gene's LOEUF score, 0.13, which puts it in group 1 of 6, group 1 being the genes least tolerant of losing a copy. Missense variants: 413 observed, 563.18 expected, observed/expected ratio (o/e) 0.73, 90% interval 0.68 to 0.8. Synonymous variants: 186 observed, 207.93 expected, observed/expected ratio (o/e) 0.89, 90% interval 0.79 to 1.01.
Homologues: Orthologues: chimpanzee CPSF7 (100% identical), macaque CPSF7 (100% identical), dog CPSF7 (99% identical), pig CPSF7 (99% identical), rabbit CPSF7 (99% identical), mouse Cpsf7 (99% identical), rat Cpsf7 (98% identical), guinea pig CPSF7 (98% identical), tropical clawed frog cpsf7 (58% identical), Drosophila melanogaster Cpsf6 (44% identical), Caenorhabditis elegans cfim-2 (30% identical). Paralogues in human: CPSF6 (52% identical).
Diseases named in the same sentence as CPSF7 in open-access papers:
CPSF7 is named in the same sentence as 12 diseases in open-access papers, as found by Europe PMC text mining. Sharing a sentence is not in itself a finding about the gene and the disease. The quoted sentences say what the papers report.
breast carcinoma (4 papers, 2013 to 2024). "CPSF7 can play a regulatory role in polyA site selection and it is found to be significantly associated with tumor recurrence in breast cancer recently." (PMID 27764782, 2016). "Three novel miR-26b targets were identified (TNKS1BP1, CPSF7, COL12A1), and the expression of each in cancer stroma shown to be significantly associated with breast cancer recurrence." (PMID 27078844, 2016). "In addition, three novel miR-26b targets were identified (TNKS1BP1, CPSF7, COL12A1) and the expression of each in cancer stroma was shown to be significantly associated with breast cancer recurrence." (PMID 23939832, 2013). "Enrichment difference analysis of the genes showing changes after OHT treatment revealed known breast cancer oncogenes such as HDAC3, UBE2C and CPSF7 among the depleted genes and reported breast cancer suppressors such as CSK, SPRED2 and TSC2 among the enriched genes." (PMID 38914552, 2024). "For each gene, high expression, as seen in 26bk/d cells, was significantly associated with increased rates of recurrence (log rank, TNKS1BP1 p = 0.002, CPSF7 p = 0.007, COL12A1 p = 0.043), implicating them, and by inference miR-26b, as stromal determinants of breast cancer outcome." (PMID 23939832, 2013).
lung adenocarcinoma (4 papers, 2020 to 2022). A carcinoma that arises from the lung and is characterized by the presence of malignant glandular epithelial cells. "This study aims to uncover the function and underlying mechanism of CPSF7 in lung adenocarcinoma (LUAD)." (PMID 36349192, 2022). "CPSF7 was recently associated with lung adenocarcinoma, further highlighting the potential relevance of our results because IPF and lung cancer share several pathological mechanisms." (PMID 32486318, 2020). "LINC009581 elevated the expression of CPSF7 by acting as a miR-625-5p sponge, which accelerated the development and progression of lung adenocarcinoma, thereby demonstrating that LINC009581 might be utilized as a promising therapeutic target for lung adenocarcinoma." (PMID 34337069, 2021).
liver cancer (3 papers, 2021 to 2025). An epithelial or non-epithelial malignant neoplasm that arises from the liver. "For instance, piperlongumine, a natural alkaloid, has been shown to enhance sorafenib’s antitumor activity by mediating ROS-AMPK activation and targeting CPSF7 in liver cancer." (PMID 40242448, 2025). "On the other hand, piperlongumine has been demonstrated to synergistically enhance the antitumor activity of sorafenib by mediating ROS-AMPK activation and targeting CPSF7 in liver cancer cells." (PMID 37175755, 2023). "For example, Ji and colleagues found CPSF7 is activated and regulates liver cancer growth and metastasis by targeting the WWP2/PTEN/AKT signaling pathway." (PMID 33648552, 2021).
lung carcinoma (3 papers, 2020 to 2023). "As an important component of APA, CPSF is usually upregulated in cancers, such as CPSF1 in HCC and ovarian cancer, CPSF3 in HCC, CPSF4 in colorectal and lung cancers, and CPSF7 in HCC." (PMID 36349192, 2022). "Indeed, RT–PCR results indicated that the deletion of MEN1 in lung cancer cells increased the instances of short splicing isoforms in the FAM189B, NUBP2, ENDOV and TARBP2 genes, but inhibited generation of the CPSF7, MRRF and LETMD1 splicing isoforms." (PMID 37395406, 2023).
HIV-1 infection (2 papers, 2023 to 2026). The type species of lentivirus and the etiologic agent of acquired immunodeficiency syndrome (AIDS). "As a control, we quantified the percentage of cells containing CPSF5, CPSF6, and CPSF7 in nuclear speckles upon HIV-1 infection of wild-type and CPSF6-KO cells." (PMID 41405390, 2026). "To further characterize the condensates induced by HIV-1 infection, we used colocalization experiments to assess the presence of CPSF5 and/or CPSF7 in CPSF6 condensates." (PMID 37414787, 2023). "However, we found no accumulation of CPSF7 in condensates suggesting that HIV-1 infection does not induce accumulation of the tetramer CPSF52-CPSF72." (PMID 37414787, 2023). "Our experiments revealed that CPSF5, but not CPSF7, co-localized with CPSF6 upon HIV-1 infection." (PMID 37414787, 2023).
colorectal cancer (1 paper, 2022). A primary or metastatic malignant neoplasm that affects the colon or rectum. "Some examples of long non-coding RNA variants in this catalog include rs6983267 in CCAT2 regulating cancer metabolism through allele-specific binding of CPSF7 and rs2147578 in LAMC2-1 modulating microRNA binding to it in colorectal cancer." (PMID 35365203, 2022).
viral infection (1 paper, 2024). "Interestingly, the protein expression of CPSF6 was significantly decreased after viral infection or analogue simulation, accompanied by a decreased RNA abundance, while CPSF5 and CPSF7 (CFIm59) showed no significant changes." (PMID 38416782, 2024).
cancer (5 papers, 2013 to 2023). A tumor composed of atypical neoplastic, often pleomorphic cells that invade other tissues. "In addition, the silencing of some CPSFs has also been determined to inhibit cancer progression by inhibiting the PI3K/AKT/mTOR pathway, such as the CPSF3-PI3K/Akt/GSK-3β in HCC, CPSF4-PI3K/AKT in LUAD, and CPSF7-PTEN/AKT in HCC." (PMID 36349192, 2022).
tumor (5 papers, 2016 to 2022). "Since the AKT/mTOR signaling pathway plays an important role in tumor progression, the regulatory role of CPSF7 on this pathway was analyzed." (PMID 36349192, 2022). "The upregulations of S100A4, MARCKSL1, BCAM, BAG4, IPO4 and CPSF7 in pHAGE-ELL(C595A) tumours were confirmed." (PMID 27009366, 2016). "We found that LINC00958 knockdown could inhibit tumor growth and diminish tumor volume and weight, but then these effect was reversed by overexpressing CPSF7." (PMID 31997940, 2020).
infection (2 papers, 2024). The state of being infected such as from the introduction of a foreign agent such as serum, vaccine, antigenic substance or organism. "Although CPSF7 had a more grainy staining pattern in both HeLa cells and MDMs, it did not change upon infection with HIV-1, and it did not co-localise with the CPSF5 puncta that formed following infection in either cell type." (PMID 38793552, 2024).
CPSF7 also shares sentences with these, for which no sentence is quoted: oral carcinoma (1 paper); ovarian carcinoma (1).